MCOLN2 (mucolipin TRP cation channel 2)
Description:
Nonselective cation channel probably playing a role in the regulation of membrane trafficking events. Acts as a Ca(2+)-permeable cation channel with inwardly rectifying activity. May activate ARF6 and be involved in the trafficking of GPI-anchored cargo proteins to the cell surface via the ARF6-regulated recycling pathway. May play a role in immune processes. In adaptive immunity, TRPML2 and TRPML1 may play redundant roles in the function of the specialized lysosomes of B cells (By similarity). In the innate immune response, may play a role in the regulation of chemokine secretion and macrophage migration (By similarity). Through a possible and probably tissue-specific heteromerization with MCOLN1 may be at least in part involved in many lysosome-dependent cellular events. Also functions as a Fe(2+) permeable channel (By similarity).
Synonyms: TRPML2; FLJ36691; TRP-ML2
Tractability: Small molecule: a high-quality ligand is known; it belongs to a druggable protein family. Antibody: UniProt places it where antibodies can reach, with high confidence; its Gene Ontology location is reachable by antibodies, with high confidence; UniProt predicts a signal peptide or a membrane-spanning region. PROTAC: a small molecule that binds it is known.
Gene: Protein-coding gene on chromosome 1 (84,925,583 to 84,997,115, reverse strand). Ensembl gene ENSG00000153898.
Subcellular location: Cell membrane; Late endosome membrane; Lysosome membrane; Recycling endosome membrane
Pathways (Reactome):
Transport of small molecules: TRP channels
Gene Ontology:
Molecular function: protein binding; calcium channel activity; iron ion transmembrane transporter activity; NAADP-sensitive calcium-release channel activity; identical protein binding; monoatomic cation channel activity
Biological process: calcium ion transmembrane transport; calcium-mediated signaling; iron ion transmembrane transport
Cellular component: late endosome membrane; lysosomal membrane; plasma membrane; recycling endosome membrane; membrane; recycling endosome
Genetic constraint (gnomAD): Loss-of-function variants: 39 observed, 49.07 expected, observed/expected ratio (o/e) 0.79, 90% interval 0.61 to 1.04. The upper end of that interval is the gene's LOEUF score, 1.04, which puts it in group 4 of 6, group 1 being the genes least tolerant of losing a copy. Missense variants: 478 observed, 548.94 expected, observed/expected ratio (o/e) 0.87, 90% interval 0.81 to 0.94. Synonymous variants: 188 observed, 193.59 expected, observed/expected ratio (o/e) 0.97, 90% interval 0.86 to 1.1.
Homologues: Orthologues: chimpanzee MCOLN2 (99% identical), macaque MCOLN2 (97% identical), dog MCOLN2 (88% identical), pig MCOLN2 (85% identical), guinea pig MCOLN2 (83% identical), rabbit MCOLN2 (81% identical), rat Mcoln2 (80% identical), mouse Mcoln2 (80% identical), tropical clawed frog mcoln2 (68% identical), zebrafish mcoln2 (45% identical), Drosophila melanogaster CG42638 (37% identical), Drosophila melanogaster Trpml (37% identical), and 1 more. Paralogues in human: MCOLN3 (55% identical), MCOLN1 (46% identical).
Diseases named in the same sentence as MCOLN2 in open-access papers:
MCOLN2 is named in the same sentence as 41 diseases in open-access papers, as found by Europe PMC text mining. Sharing a sentence is not in itself a finding about the gene and the disease. The quoted sentences say what the papers report.
glioma (16 papers, 2016 to 2025). A benign or malignant brain and spinal cord tumor that arises from glial cells (astrocytes, oligodendrocytes, ependymal cells). "Higher levels of TRPC4, TRPC6, MCOLN1, MCOLN2, and MCOLN3 were significantly associated with shorter OS times in glioma." (PMID 35625048, 2022). "In our present study, the results showed that the expression of TRPC1 and TRPC3 was significantly increased in glioma with IDH mutation status and 1p/19q codeletion status, while the expression of TRPC6, MCOLN1, MCOLN2, and MCOLN3 was significantly decreased." (PMID 35625048, 2022). "Among the eight final identified hub genes, higher expression levels of TRPC1, TRPC3, and TRPC5 were significantly associated with longer OS time in glioma, while higher expression levels of TRPC4, TRPC6, MCOLN1, MCOLN2, MCOLN3 were significantly associated with shorter OS time." (PMID 35625048, 2022). "MCOLN2, TRPV4, and ITPR2 were significantly highly expressed in glioma tissues, and the three most significantly down-regulated genes (PRKCG, CAMK2A, and HTR2A) had lower expression in tumor tissues." (PMID 41331166, 2025). "The gene expression levels of TRPC1, TRPC3, and TRPC5 were significantly higher in low-grade glioma (LGG), while the levels of TRPC4, TRPC6, TRPM7, MCOLN1, MCOLN2, and MCOLN3 were significantly higher in high-grade glioma (HGG)." (PMID 35625048, 2022).
viral infection (6 papers, 2018 to 2025). "In both cell types, loss of MCOLN2 expression caused a significant reduction in viral infection." (PMID 29382735, 2018). "It is therefore interesting to consider the implications of MCOLN2 upregulation during viral infection in vivo, when IFN responses are systemic." (PMID 29382735, 2018). "Together, these experiments show that MCOLN2 enhances an early step in viral infection prior to replication." (PMID 29382735, 2018). "We previously identified endosomal cation channel mucolipin-2 (MCOLN2) as a host factor that promotes viral infection." (PMID 29382735, 2018). "Finally, CCR7, MBL2, and MCOLN2 have all been connected to the modulation of host cellular and immune responses in viral infection." (PMID 33705408, 2021). "If MCOLN2 enhances viral infection by increasing the efficiency of vesicular trafficking, then we hypothesized that more virus should fuse with and escape from endosomes in cells ectopically expressing MCOLN2." (PMID 29382735, 2018). "In recent screening efforts for interferon (IFN)-inducible factors that modulate viral infection, we found that mucolipin-2 (MCOLN2) enhanced the infectivity of diverse viruses, including yellow fever virus, dengue virus, influenza A virus, and equine arteritis virus." (PMID 29382735, 2018). "Deciphering these models will be important for determining whether MCOLN2-specific agonists or antagonists could be used therapeutically to modulate viral infection." (PMID 29382735, 2018). "Intriguingly, a rare genetic variant of MCOLN2 fails to enhance viral infection in our cell culture model." (PMID 29382735, 2018). "Combined with our original discovery of an MCOLN2 phenotype in a STAT1−/− background, these data suggest that MCOLN2-mediated enhancement of viral infection is not linked to impairment of IFN or ISG induction." (PMID 29382735, 2018). "Last, we found that a rare genetic variant of human MCOLN2 fails to enhance viral infection when ectopically expressed in cell culture." (PMID 29382735, 2018). "MCOLN2 channel activity is necessary for enhancement of viral infection." (PMID 29382735, 2018). "Here, we characterize the mechanism by which MCOLN2 enhances viral infection." (PMID 29382735, 2018). "A rare genetic variant of human MCOLN2 fails to enhance viral infection." (PMID 29382735, 2018). "However, the specific effects of MCOLN2 on viral infection are unknown." (PMID 29382735, 2018). "Under these conditions, MCOLN2 no longer enhanced viral infection." (PMID 29382735, 2018). "Besides, LY6E and MCOLN2 directly enhance viral infection rather than inhibit IFN signaling." (PMID 40245000, 2025). "In this regard, a rare genetic variant of human TRPML2, which induces a lysine/glutamine or arginine change at 370 aa in TM3 and TM4 domains of TRPML2 protein (MCOLN2-K370Q), failed to enhance TRPML2-mediated viral infection when ectopically expressed." (PMID 32425938, 2020). "MCOLN2 promoted ISG but not IFNB1 expression in response to SINV, despite having a net positive effect on viral infection." (PMID 29382735, 2018).
acute lymphoblastic leukemia (4 papers, 2020 to 2022). Leukemia with an acute onset, characterized by the presence of lymphoblasts in the bone marrow and the peripheral blood. "In addition, the MCOLN2 protein expression level may regulate the development of paediatric acute lymphoblastic leukaemia." (PMID 35222533, 2022). "Increased TRPML2 expression in HN31 oral cancer cells and downregulation of the MCOLN2 gene, due to DNA methylation, in pediatric acute lymphoblastic leukemia, lung adenocarcinoma and squamous cell carcinoma were reported." (PMID 35887088, 2022).
prostate carcinoma (3 papers, 2022 to 2025). A carcinoma that arises from epithelial cells of the prostate gland. "TRPML1, encoded by gene MCOLN1, and TRPML2, encoded by gene MCOLN2, were expressed at moderate to high levels in 80% and 90% of the prostate cancer samples examined." (PMID 40332161, 2025). "MCOLN2 was also over-expressed in the TCGA prostate cancer cohort, although in somewhat lower levels (mean mRNA expression z score compared to normal samples = 1.34, SD = 1.2)." (PMID 40332161, 2025). "Prostate cancers with high MCOLN2 mRNA expression were more frequently (69.9% of cases) positive for ERG fusions than cancers with low MCOLN2 mRNA expression (26.5% of cases positive, Fisher’s exact test p = 0.0001)." (PMID 40332161, 2025). "In contrast to our results that suggest that high MCOLN2 mRNA expression may be associated with better biochemical relapse-free survival outcomes, another study implied a worse overall survival of prostate cancers with high MCOLN2 mRNA." (PMID 40332161, 2025). "Prostate cancers with MCOLN2 over-expression (mean mRNA expression z score compared to normal samples > 2, n = 73) in the MSK prostate cohort were compared with prostate cancers with lower MCOLN2 mRNA expression (n = 77) from the same cohort." (PMID 40332161, 2025). "At the mRNA level, MCOLN2 and TRPM4 were strongly expressed in a sub-set of prostate cancers." (PMID 40332161, 2025). "However, neither ERG nor AR possess clustered promoter binding sites in the promoter of the MCOLN2 gene and, therefore, MCOLN2 up-regulation in prostate cancers with ERG over-expression is not directly performed by these transcription factors." (PMID 40332161, 2025).
lung adenocarcinoma (2 papers, 2018 to 2022). A carcinoma that arises from the lung and is characterized by the presence of malignant glandular epithelial cells. "To test whether the enhancing effect of MCOLN2 extends to other cellular backgrounds, we stably expressed MCOLN2 or an empty vector in human A549 lung adenocarcinoma cells and challenged cells with IAV." (PMID 29382735, 2018).
Arrhythmia (1 paper, 2021). Any cardiac rhythm other than the normal sinus rhythm. "These alterations in RV may contribute to impaired Ca-cycling, especially since Mcoln2 has been linked to arrhythmias in GWAS data from the GWASdb SNP-Phenotype Associations dataset." (PMID 34204946, 2021). "Other RV-specific transcriptional changes, which may contribute to the observed phenotype, included underexpression of Slc26a3, which controls intracellular pH and may impact Ca-cycling, and upregulation of Mcoln2, which may participate in Ca-overload and potential arrhythmia." (PMID 34204946, 2021).
bipolar disorder (1 paper, 2011). A disorder of the brain that causes unusual shifts in mood, energy, activity levels and the ability to carry out day-to-day tasks. "The protein Mucolipin-2, encoded by gene MCOLN2 and also known as TRPML2 (transient receptor potential cation channel, mucolipin subfamily, member 2), has been confirmed to have strong associations with bipolar disorder in a family-based association study." (PMID 21569557, 2011).
cognitive decline (1 paper, 2024). "Constitutive activity of MCOLN2 induces cell degeneration and might play a role in the irreversible brain damage and cognitive decline associated with frequent and recurrent epileptic seizures." (PMID 38383918, 2024).
colorectal cancer (1 paper, 2024). A primary or metastatic malignant neoplasm that affects the colon or rectum. "Elevated expression levels of PAX6, BCL11B, MCOLN2, CUX1 and EMX1 reported in colorectal cancer positively correlate with TRPA1 in other malignancies, with a possible implication in tumorigenesis." (PMID 39770499, 2024).
prostate adenocarcinoma (1 paper, 2025). "In the present study, we analyzed publicly available multiomic data to show that the expression of the TRP channel TRPML2, which is frequently over-expressed in prostate adenocarcinomas and encoded by the MCOLN2 gene, is strongly associated with cases displaying ERG over-expression." (PMID 40332161, 2025).
ZIKV infection (1 paper, 2018). "We also found that MCOLN2 enhanced ZIKV infection by approximately 75% over control cells." (PMID 29382735, 2018).
tumor (13 papers, 2007 to 2025). "ATP13A2 and MCOLN2 protein expression levels were reduced in tumor samples when compared with normal ones, in line with the association of a better prognosis with a lower mRNA expression." (PMID 31083561, 2019). "Following the literature, a tumor-promoting activity for the up-regulation of MCOLN2 and the down-regulation of FILIP1L and BCL2L10 can be hypothesized." (PMID 32911675, 2020). "The three genes (MCOLN1, MCOLN2, and MCOLN3) coding for the mucolipin subfamily of TRP channels were also down-regulated in tumor tissues." (PMID 24466154, 2014). "We also found two other significant genes—MCOLN2 and TRPC1—in tumor stage III patients." (PMID 31083561, 2019).
cancer (9 papers, 2016 to 2025). A tumor composed of atypical neoplastic, often pleomorphic cells that invade other tissues. "A 16-gene signature, including the Wnt/β−catenin signaling pathway and the MCOLN2 gene, was found to be associated with cancer recurrence, metastasis and distinct survival patterns in breast cancer patients." (PMID 35054871, 2022).
infection (5 papers, 2018 to 2025). The state of being infected such as from the introduction of a foreign agent such as serum, vaccine, antigenic substance or organism. "In addition, CCR5-deficiency during infection affected the upregulation of cytokine genes such as Csf2, Csf3, Cxcl1, Edn1, and Il6 and other genes associated with immune response (i.e., Gimap6, Mcoln2) and migration (i.e., Cyfip2)." (PMID 31506064, 2019). "We conducted transcriptomics at 16 h post infection (hpi), near maximum divergence of replication inside wild-type vs. MCOLN2−/− THP-1s and prior to restriction in wild-type THP-1s." (PMID 37228749, 2023). "The genetic interaction of a magnesium importer mutant with murine host Mcoln2 genotype (p = 0.0002) leads us to conclude that murine Mcoln2, like human MCOLN2, affects Mg2+ accessibility by Salmonella during infection." (PMID 37228749, 2023). "Our study identifies MCOLN2 as a novel endosomal host factor that facilitates viral vesicular trafficking to ultimately promote productive infection." (PMID 29382735, 2018). "Together, these data indicate that endogenous MCOLN2 is required for optimal infection in diverse cell types and that infection can be enhanced by ectopic MCOLN2 expression." (PMID 29382735, 2018). "After infection, there was a significant increase in dequenched R18 signal in MCOLN2-expressing cells, indicating that ectopic MCOLN2 expression promotes fusion of IAV." (PMID 29382735, 2018). "In previous screening efforts, we showed that MCOLN2 enhances infection of viruses from multiple families, including yellow fever virus (YFV) (Flaviviridae), influenza A virus (IAV) (Orthomyxoviridae), and equine arteritis virus (EAV) (Arteriviridae)." (PMID 29382735, 2018). "The induction of MCOLN2 expression in activated immune cells therefore provides two mechanisms whereby this channel could regulate infection—Ca2+ currents regulating endocytic events and Mg2+ currents affecting Mg2+ acquisition." (PMID 37228749, 2023). "We then compared these three groups to infection data in MCOLN2-expressing cells." (PMID 29382735, 2018). "Therefore, the transcriptomics and phoPQ mutant infection data suggested a simple hypothesis: MCOLN2 deprives S. Typhi of Mg2+." (PMID 37228749, 2023). "To determine whether MCOLN2 channel activity is important for its viral enhancing effect, we tested the infection phenotype of a well-characterized dominant-negative mutant, referred herein as MCOLN2-DD/KK, in which two conserved aspartates D463 and D464 are mutated to lysine." (PMID 29382735, 2018). "Thus, MCOLN2-mediated enhancement of infection may represent a key vulnerability in the viral life cycle that could be targeted for therapeutic intervention." (PMID 29382735, 2018). "Additionally, MCOLN2 expression still enhanced infection by the labeled virus." (PMID 29382735, 2018).
MCOLN2 also shares sentences with these, for which no sentence is quoted: glioblastoma (7 papers); breast carcinoma (3); infectious disease (2); mucolipidosis type IV (2); myeloma (2); neurodegenerative disease (2); anaplastic astrocytoma (1); astrocytomas (1); atherosclerosis (1); bacterial infection (1); bladder cancer (1); brain tumors (1); deafness (1); epilepsy (1); iron deficiency (1); liver disease (1); liver fibrosis (1); Multiple Myeloma (1); multiple sclerosis (1); oral cancer (1); pilocytic astrocytoma (1); psoriasis (1); retinal degeneration (1); rheumatoid arthritis (1); Salmonellae infections (1); Seizure (1); squamous cell carcinoma (1).